CAT (catalase)
Diseases named in the same sentence as CAT in open-access papers (continued):
Sharing a sentence is not in itself a finding about the gene and the disease.
endothelial dysfunction (30 papers, 2009 to 2025). In vascular diseases, endothelial dysfunction is a systemic pathological state of the endothelium (the inner lining of blood vessels) and can be broadly defined as an imbalance between vasodilating and vasoconstricting substances produced by (or acting on) the endothelium. "Considering that ID affects the production of various antioxidant enzymes such as catalase and cytochrome oxidase, ID can also lead to oxidative damage and endothelial dysfunction." (PMID 35067842, 2022). "It expresses antioxidant enzymes such as superoxide dismutase, catalase, and glutathione peroxidases (GPx) to prevent endothelial dysfunction." (PMID 31248152, 2019). "However, mesenteric arteries of WT mice incubated with the combination of catalase and diclofenac showed an endothelial dysfunction." (PMID 39456432, 2024). "In addition, SIRT1 deacetylates FOXOs and stimulates FOXO-dependent antioxidant [such as catalase (CAT), manganese superoxide dismutase (MnSOD) and thioredoxin] expression to eliminate ROS in endothelial cells, and prevent endothelial dysfunction 78-80." (PMID 35813294, 2022). "Our previous studies demonstrated that HT induces the proliferation of VECs and protects the cells against H2O2 damage by the stimulation of Nrf2/HO-1 pathway, and raising catalase expression, which appears to be crucial to prevent early endothelial dysfunction." (PMID 24066302, 2013). "Endothelial dysfunction, which was manifested in the form of diminished NO bioavailability, was well compensated for by an increased expression of KCa3.1 protein, as shown in aged wild‐type, CerS2 null, and catalase−/−/GPX1−/− mice, and an upregulation of KCa3.1 channel activity." (PMID 27363720, 2016). "An evident imbalance between pro-oxidants, which are high due to various components in cigarette smoke, and antioxidants in the body such as superoxide dismutase (SOD), catalase (CAT) and gluthatione peroxidase (GPx) lead to endothelial dysfunction." (PMID 36071890, 2021). "Hence, PA-BSA-induced endothelial dysfunction was accompanied by elevated ROS generation and was ameliorated by treatment with antioxidant enzymes (SOD and CAT)." (PMID 41465574, 2025). "These toxicants interfere with the balance of key antioxidant enzymes such as superoxide dismutase (SOD), catalase (CAT), and glutathione peroxidase (GPx), thereby exacerbating oxidative stress and contributing to endothelial dysfunction and vascular impairment." (PMID 40728952, 2025). "Previously, we established that TRAF6 inhibition partially prevented endothelial dysfunction, weight gain, increase in HbA1c values, oxidative burst of whole blood leukocytes, cardiac RAGE signaling, vascular ROS formation, and impaired catalase/glutathione peroxidase 1 expression in db/db mice." (PMID 38554187, 2024). "In endothelial dysfunction, genistein can effectively inhibit ROS and malondialdehyde (MDA) in cells, and restore the four oxidoreductases activities including superoxide dismutase (SOD), catalase (CAT), glutathione (GSH) and glutathione peroxidase (GPx)." (PMID 36909175, 2023). "Catalase (20000 U/mL, 30 min) pretreatment of rat aortic rings significantly prevented the H2O2-mediated disruption of ACh-induced EDR, albeit only partially, suggesting that H2O2 exerts both direct and indirect effects to induce endothelial dysfunction." (PMID 25258643, 2014). "Moreover, SIRT1 deacetylates FoxO proteins and thus stimulates FoxO-dependent anti-oxidative enzymes, such as catalase (CAT), manganese superoxide dismutase (MnSOD), and thioredoxin (TRX), eliminating ROS from endothelial cells and thus preventing endothelial dysfunction." (PMID 38003402, 2023).
diabetic nephropathy (29 papers, 2013 to 2025). "Another researcher also reported that CAT deficiency accelerated diabetic nephropathy by impairing peroxisomal/mitochondrial biogenesis and fatty acid oxidation." (PMID 33477607, 2021). "Suppression of ROS formation attenuated renal interstitial fibrosis and tubular apoptosis in db/db transgenic mice, and catalase deficiency increased mitochondrial ROS accompanied with renal fibrosis in diabetic nephropathy mice." (PMID 24349535, 2013). "Improved glucose and lipid metabolism, inhibited excessive weight gain, relieved kidney tissue injury, activated NRF2/HO-1 pathway, and enhanced CAT activity in diabetic nephropathy complications." (PMID 40686811, 2025). "The results indicated a statistically significant difference in CAT activity between the diabetic nephropathy groups, DMT2N1 (p = 0.000128) and DMT2N2 (p = 0.00013), and diabetic patients without complications, DMT2N0." (PMID 37686346, 2023). "Pan and colleagues highlighted the antioxidant potential of Ganoderma lucidum in diabetic nephropathy in rats, as it reduced lipid peroxidation and increased CAT activity." (PMID 35739932, 2022). "The findings of this study are consistent with the findings of Amouoghli-Tabrizi and Mohajeri on serum urea level and kidney tissue catalase level in a study on the effect of hydroalcoholic Brassica rapa root extract on premature diabetic nephropathy in rats." (PMID 28487873, 2017). "In agreement with our findings, previous studies also demonstrated that the beneficial effect of sulodexide on diabetic nephropathy was associated with the reduction of the MDA levels and enhancement of SOD and catalase activities." (PMID 28036282, 2017). "Dapagliflozin also significantly increased the expression levels of the antioxidant enzymes, including Cu/ZnSOD, MnSOD, and catalase in diabetic nephropathy." (PMID 27802313, 2016). "One might assume that the increased catalase activity in the kidney of diabetic rats may represent a compensatory or adaptive response to increased oxidative damage in diabetic nephropathy." (PMID 37016650, 2023). "Notably, in a rodent model of alloxan-induced diabetic nephropathy, diosmin at 50 and 100 mg/kg administered per os was shown to significantly increase the activity of superoxide dismutase, catalase, and glutathione." (PMID 37513462, 2023). "In a study involving hemodialysis patients with diabetic kidney disease, the activity of the antioxidant enzymes catalase (CAT), superoxide dismutase (SOD), and glutathione peroxidase (GSH-Px) was assessed, and IL-6 and TNF-α levels were determined as an indicator of oxidative stress." (PMID 36615736, 2022). "Therefore, endogenous CAT plays an important role in protecting against diabetic nephropathy by decreasing oxidative stress through the regulation of intrarenal RAS and peroxisomal metabolism." (PMID 33477607, 2021). "Furthermore, it was found that C3G could increase the Nrf2 mRNA expression and enhance SOD, CAT, and GPx activities in renal cells of mice with diabetic nephropathy." (PMID 38628219, 2024). "In rats with STZ-induced diabetic nephropathy, treatment with CM (50 ml/day, for 8 weeks), increased SOD and CAT expression, CAT activity and GSH levels, as well as reducing fat peroxidation." (PMID 35493477, 2022). "In fact, in agreement with other research, in which the antioxidant protective effect on the diabetic nephropathy progression was demonstrated, we found that RLE restored the antioxidant pathways, in particular SOD, CAT, and GPx activities." (PMID 32466228, 2020).
diabetic nephropathy (continued). "Furthermore, LS has been proven to have antioxidant properties in a rat model of diabetic nephropathy produced by streptozotocin, as demonstrated by a decrease in renal MDA levels and an increase in renal SOD, catalase, and GSH levels." (PMID 40542040, 2025). "Butyrate (1 g/kg/day) addition in the diet significantly inhibited the decrease in catalase (CAT), glutathione peroxidase (GSH-Px), and superoxide dismutase (SOD) in a randomized controlled trial involving a mouse model of diabetic nephropathy-induced skeletal muscle atrophy." (PMID 40362771, 2025). "Furthermore, a meta-analysis study has shown that RES has positive effects on diabetic nephropathy by inducing the activities of AOEs, such as SOD, CAT, GSH, and GPx." (PMID 38058997, 2023). "Serum bilirubin levels are positively correlated with the levels of the antioxidative enzymes as superoxide dismutase, catalase, and glutathione peroxidase, while it is inversely correlated with C-reactive protein, TNF-α, interleukin (IL)-2, IL-6, and IL-10 release in diabetic kidney disease." (PMID 35327498, 2022).
gastric cancer (29 papers, 2009 to 2025). A primary or metastatic malignant neoplasm involving the stomach. "In this study, we investigated the association between gastric cancer and the polymorphisms of CAT C-262T and SOD1 A251G." (PMID 27843986, 2014). "High catalase expression has been observed in certain human cancer cell lines, including gastric cancer exposed to cisplatin chemotherapy." (PMID 38748263, 2024). "A previous study with gastric carcinoma cells demonstrated that inhibition of CAT allowed selective reactivation of the NO/peroxynitrite pathway, thus revealing the role of this enzyme in the catabolism of this factor." (PMID 38338793, 2024). "Third, another interesting pattern of our work was that we determined a severe increase in the concentrations of SOD and CAT in the blood plasma of patients with stages III–IV gastric cancer." (PMID 35626358, 2022). "No statistical difference was observed when GSH and MDA levels and catalase activity when comparing between the gastric cancer stages I/II and III/IV." (PMID 34873431, 2021). "Catalase and superoxide dismutase activity were lower in the gastric cancer group (3.82 vs. 0.91; p < 0.001 and 1.04 vs. 0.6; p < 0.001) compared to their first-degree relatives." (PMID 34873431, 2021). "In MNNG gastric cancer rat model, administration of 50, 100 or 150 mg/kg body weight of lycopene caused an increment in antioxidant enzymes as expected (SOD, CAT, GSH-Px) and increment in cytokines (IL-2, IL-4, IL-10, TNF-α) and antibodies (IgG, IgA, IgM)." (PMID 34202203, 2021). "MKN-45 human gastric carcinoma cells at low cell density were either treated with neutralizing monoclonal antibodies directed towards catalase or irrelevant control antibodies." (PMID 34679719, 2021). "Anticancer drugs also increased catalase levels in oral cancer cells, bladder cancer cells, pancreatic cancer cells, and gastric cancer cells." (PMID 31658599, 2019). "Overexpression of catalase has been detected in various carcinomas, such as chronic myeloid leukemia, gastric cancer, and skin cancer." (PMID 31658599, 2019). "SOD and CAT levels are significantly reduced in patients with gastric and duodenal ulcers and even in gastric cancer patients." (PMID 25610477, 2014). "In the present study, we investigated possible associations between polymorphisms of CAT C-262T (rs1001179) and SOD1 A251G (rs2070424) with susceptibility to gastric cancer." (PMID 27843986, 2014). "The decrease in catalase activity at all stages of gastric cancer infected with H. pylori is probably due to substrate inhibition by excess hydrogen peroxide, which, on the other hand, causes an increase in the activity of the enzyme glutathione peroxidase for its neutralization." (PMID 40806737, 2025). "The dynamics of changes in the content of SOD and CAT in the plasma in patients with gastric cancer may be a target of future investigations." (PMID 35626358, 2022). "The human gastric carcinoma cell line MKN-45 is a prototype of bona fide tumor cells, as it is protected from the NADPH oxidase-1 (NOX-1)-driven HOCl- and nitric oxide (NO)/peroxynitrite apoptosis-inducing signaling pathways by a membrane-associated catalase." (PMID 34679719, 2021). "Interestingly it is reported that MDA levels and CuZn-SOD activity are significantly higher and GPx and catalase activities are significantly lower in erythrocytes of patients with oesophageal or gastric cancer than clinically healthy individuals." (PMID 27159386, 2016). "In line with this hypothesis, patients with stomach cancer at early stages were found to exhibit a similar compensatory defense reaction, involving an increase of CAT activity likely attributable to a decrease of GSH-PX and a resultant increase of GSH." (PMID 26783415, 2016). "In patients with gastric cancer stages III–IV, differences were found in the form of a slight increase in the concentration of SOD and a severe increase in the content of CAT." (PMID 35626358, 2022).
gastric cancer (continued). "Patients with peptic ulcers and gastric cancer display significantly reduced levels of SOD and CAT levels." (PMID 33066164, 2020). "To verify the effects of 17-DMAG on the expression of antioxidant enzymes, we examined the expression of representative antioxidants (MnSOD, catalase, and GPx) in AGS gastric cancer cells." (PMID 28915605, 2017). "In this study, the potential target of HL-RG in the treatment of gastric cancer was studied Through PPI network analysis and molecular pairing, TGFB1, CCND1, MMP9, ERBB2, CAT, and PPARα may be the core targets of HL-RG in the treatment of RCC." (PMID 41305721, 2025). "The hub proteins identified, CAT, PLEKHA4, HSP90AB1, TXN, EEF2, H6PD, and PDIA3, may play important roles in the treatment of gastric cancer using nintedanib." (PMID 38406279, 2024). "We found that, in those with gastric cancer who were not given neoadjuvant chemotherapy, the levels of CAT, GSH and SOD were significantly lower than in the control group, while the levels of MDA and NO increased significantly." (PMID 37274227, 2023). "The antioxidative activity in cancer could also be observed in upregulation of both SOD, CAT and suppressed MDA production under lycopene administration to gastric cancer rat model." (PMID 34202203, 2021). "An in vivo test in gastric cancer mice showed that TPS fraction with small MW showed stronger promoting effect on stomach antioxidant enzymes such as superoxide dismutase (SOD), catalase (CAT) and glutathione peroxidase (GSH-Px)." (PMID 27809221, 2016). "In gastric cancer, interleukins (IL-2 and IL-4) and TNF-α were enhanced by polysaccharides that also provide dose-dependent protection against N-methyl-N'-nitro-N-nitrosoguanidine (MNNG) induced oxidative injury by enhancing Superoxide dismutase (SOD), catalase (CAT), and glutathione (GSH-Px)." (PMID 36193066, 2022).
pancreatic cancer (29 papers, 2009 to 2025). "Nqo1 is overexpressed in pancreatic tumour versus the associated normal tissue; however, catalase expression reduces in comparison to the levels related to normal pancreas tissues." (PMID 35180880, 2022). "The addition of bovine catalase to cell media prevented the synergistic effect of Au/P-AscH− in pancreatic cancer cells." (PMID 35624835, 2022). "Increased NQO1/decreased catalase expression is observed in pancreatic intraepithelial neoplasia, precursor lesions of pancreatic cancer." (PMID 34789190, 2021). "Taking in consideration only the biopsies of the three types of tumors analyzed, our data found that CAT expression, was high in the 43% of pancreatic carcinoma biopsies, in the 40% of colorectal biopsies and in the 60% of glioblastoma samples." (PMID 33540681, 2021). "Targeting NQO1:Catalase ratios of pancreatic cancers requires selective and potent NQO1 bioactivatable compounds." (PMID 33214574, 2020). "The NQO1/Catalase ratios demonstrated in pancreatic cancers (SF1) revealed a dramatic potential therapeutic window that can be exploited by NQO1 bioactivatable drugs, such as ARQ761 (ß-lapachone), currently in clinical trials (NCT01502800)." (PMID 26602448, 2015). "The high NQO1/Catalase ratios in pancreatic cancers strongly suggest that NQO1-overexpressing PDA cancer cells will respond to NQO1 bioactivatable drugs by producing supralethal doses of H2O2." (PMID 26602448, 2015). "Ethanol decreases the expression of cytosolic antioxidant enzymes including manganese superoxide dismutase, catalase, and glutathione peroxidase in pancreatic tissue from chronic pancreatitis and pancreatic cancer." (PMID 24244749, 2013). "SOD2 expression is higher than SOD1, SOD3, and CAT in pancreatic cancers." (PMID 37891871, 2023). "As a proof-of-concept, over-expression of catalase by transient transfection completely blocked capsaicin mediated ROS generation and apoptosis in BxPC-3 cells demonstrating its critical role in the survival of pancreatic cancer cells." (PMID 21647434, 2011). "A recent study examining the role of catalase in pancreatic cancer demonstrated that catalase knockout cells exhibited greater radiosensitization to P-AscH− and that cancer cells in long-term survivors may express lower levels of catalase than cancer cells in short-term survivors." (PMID 35624835, 2022). "However, catalase could only, in part, prevent the reduction in pancreatic cancer cell growth induced by EGCG." (PMID 31590367, 2019). "It is noteworthy that catalase inhibition is a promising strategy to advance the combination treatment of PAA-TiOx NPs and X-ray radiation in pancreatic cancer cells." (PMID 39942733, 2025). "After Bmi1 knockdown, the expression of antioxidant genes including CAT, MnSOD, GSTO1, NQO1 and SOD decreased significantly in pancreatic cancer cells." (PMID 27177084, 2016). "We also noted the divergence of human pancreatic cancer cell lines, where NQO1 levels were substantially higher than in tumor tissue and Catalase levels are extremely varied." (PMID 26602448, 2015). "Furthermore, downregulation of antioxidant enzymes such as catalase (CAT) in A549 cells and glutathione (GSH) in the human PaCa-44 pancreatic cancer cell line has been reported to contribute to the accumulation of intracellular ROS." (PMID 37511450, 2023). "In pancreatic cancer, overexpression of reactive oxygen species (ROS)-detoxifying genes superoxide dismutase 2 (SOD2) and catalase (CAT) and downregulation of gemcitabine-metabolizing enzyme deoxycytidine kinase (DCK) confers cellular chemoresistance through exosome-derived miRNA-155." (PMID 33396739, 2020). "Importantly, the majority of solid cancers including lung, colon, breast, and pancreatic cancer express elevated levels of NQO1, and these same tumors have significantly lowered Catalase (an H2O2 detoxifying enzyme) levels." (PMID 33214574, 2020).
pancreatic cancer (continued). "We then examined whether catalase and NAC could prevent the reduction in pancreatic cancer cell growth induced by EGCG." (PMID 31405071, 2019). "Moreover, we detected AgNP-induced disturbance of antioxidant system (SOD1, SOD2, GPX-4, CAT, and SOD3) in pancreatic cancer cells." (PMID 30186549, 2018). "Moreover, an adenovirus containing catalase was shown to affect the activity of apoptosis signal-regulating kinase 1, which activity is dependent on H2O2 and indirectly related to HIF1 in pancreatic cancer cells." (PMID 26222311, 2015). "Besides, we also noted that rhoifolin dramatically elevated the levels of SOD, GPx, and catalase in pancreatic cancer cells; however, elevated levels of SOD, GPx, and catalase induced by rhoifolin also could be significantly attenuated by SC79 or SP600125." (PMID 35383226, 2022). "The invasion of pancreatic cancer cells resulting from the activation of the H2O2/MAPK axis under high glucose conditions is effectively inhibited by PD 98059 (ERK inhibitor), SB 203580 (p38 MAPK inhibitor), polyethylene glycol-conjugated catalase (PEG-CAT), or the siRNA specific to SOD2." (PMID 26439801, 2015).